CD4 (CD4 molecule)
Diseases named in the same sentence as CD4 in open-access papers (continued):
Sharing a sentence is not in itself a finding about the gene and the disease.
tumor (continued). "The combination of all three inhibitors resulted in a tumor microenvironment characterized by increased IFNγ-producing CD4+ T cells, decreased CD4+FOXP3+ T regulatory cells (Tregs), and decreased IL-10-producing CD4+ T cells." (PMID 40904502, 2025). "A reassessment of the primary tumor and the lung metastasis confirmed that they were PD-L1 negative, though tumor-infiltrating lymphocytes (CD3+ and CD45+) were present, with more CD8+ cytotoxic T cells than CD4+ helper T cells." (PMID 40932009, 2025). "Taken together, these data suggest that mMGL1 receptor may alter CD4+ and CD8+ T‐cell functions, mainly in the tumor microenvironment, potentially contributing to tumor growth." (PMID 40033767, 2025). "Flow cytometric analysis revealed a significant increase in the absolute count per milligram of the tumor tissue for CD3+, CD4+, and CD8+ T cells along with CD19+ B cells, natural killer cells, and M1-like macrophages in the CBD-treated mice as compared to the vehicle-treated mice." (PMID 40475776, 2025). "MHC-II molecules in microglia and dendritic cells are necessary for the CD4+ T cell response and tumor suppression, regardless of tumor cell MHC-II expression." (PMID 40332008, 2025). "Moreover, P-NLC-Chi-siRNA significantly reduced the PD-L1 mRNA expression both in vitro and in vivo, leading to enhanced CD4+ and CD8+ T-cell responses, thereby augmenting the synergistic antitumor effect in tumor xenograft models." (PMID 40286130, 2025). "Furthermore, HGGs are known to be resistant to immune checkpoint blockade therapy, partly due to a subpopulation of CD4 + T cells that express CXCL8 and contribute to tumor growth and reduced efficacy of immune checkpoint inhibitors." (PMID 41432874, 2025). "Both CD4+ and CD8+ T cell numbers were diminished in old tumor lesions." (PMID 41332581, 2025). "Although the overall cell ratio did not change significantly, CD4+ T cells showed upregulation of exhaustion markers in tumor tissues." (PMID 40740774, 2025). "Oppositely, the p38 blockade did not affect the proportion of tumor infiltrating regulatory T cell (Treg) populations expressing CD4+CD25+Foxp3+ markers, suggesting that the observed effects on CD8+ T cell exhaustion are not related to Treg populations." (PMID 41282257, 2025). "Notably, our study revealed a significant correlation between tumor markers (β-HCG and AFP) and the proportion of infiltrating CD4+ and Foxp3+ cells, as well as CTLA-4 expression." (PMID 39958339, 2025). "γδ T cells represent an emerging field in tumor immunology, and their effects on the tumor microenvironment and therapeutic applications remain unclear compared to CD8+ and CD4+ T cells." (PMID 39895781, 2025). "Also, the immunohistochemical analysis demonstrated that the rGOQD/R8 + L treatments can significantly boost the expression of CD4 and CD8 in the tumor region for photothermal immunotherapy." (PMID 40922752, 2025). "Immunoregulatory CD4 + and CD8 + Treg cells were increased over all tumor stages." (PMID 40783506, 2025). "Tumor-infiltrating T-cells isolated from both biopsy and CUSA tissue fragment materials were divided into helper (CD4+) and cytotoxic (CD8+) T-cells showing similar expression levels of PD-1, CTLA-4, and TIM-3 checkpoint receptors between biopsy and CUSA tissue fragments." (PMID 40980437, 2025). "Of the six CD4 T cell populations identified, naïve T cells and Th1-like TEM cells were found to be more abundant in blood compared to the TME, while TCM CD4 T cells and Treg/Tfh cells were overrepresented in the tumor." (PMID 39932553, 2025). "CD4+ T cells, in turn, license cDC1s through CD40-CD40L interactions, enhancing their ability to activate CD8+ T cells, thus forming a tightly regulated feedback loop that amplifies the anti-tumor response." (PMID 40475782, 2025).
tumor (continued). "Whereas obvious tumor growth was evident for the RIVA immunized mice (with RL illumination) given antibodies to block NK cells or CD4/CD8 T cells, no tumors were observed in mice lacking antibody‐mediated immune cell depletion." (PMID 40619603, 2025). "NeoAg-specific Th1 cells were detected 9 days post tumor inoculation and their frequency within the tdLN rapidly declined from approximately 25% to approximately 3% of NeoAg-specific CD4+ cells over time regardless of therapeutic intervention." (PMID 40196575, 2025). "Anti-CD4 antibody significantly suppressed tumor growth in mock-transfected tumors, while no significant suppression was observed in ULBP2-expressing tumors." (PMID 40558520, 2025). "Clinical studies have demonstrated that IL-7 plays a pivotal role in enhancing the proliferation, survival, and functional competence of both CD4+ helper T cells and CD8+ cytotoxic T lymphocytes—key effector subsets that orchestrate adaptive anti-tumor immune responses." (PMID 41450878, 2025). "These cytotoxic CD4+ T cells express granzyme K and granzyme B and exhibit the ability to kill autologous tumor cells in an MHC-II-dependent fashion, suggesting a direct role in tumor destruction." (PMID 40177538, 2025). "Hopefully, in the near future, immunohistochemical studies on the CD3, CD4, CD8 and Treg markers performed in our patient cohort might further elucidate the biology of tumor-infiltrating lymphocytes." (PMID 40563621, 2025). "The analysis revealed significant differences in the tumor microenvironment between MRD‐positive and MRD‐negative patients, particularly in macrophages (W = 15 848; p < 0.01), resting CD4 memory T cells (W = 13 249; p < 0.01), and Tfh cells (W = 10 935; p < 0.01)." (PMID 39966084, 2025). "Long-term tumor control driven by this triple combination involves CD4 T cells promoting a state of equilibrium that maintains residual tumor cells in a nonproliferative state." (PMID 40299790, 2025). "Additionally, the infiltration of both CD4+ and CD8+ T cells within tumors in CKO mice improved, potentially assisting in the effective function of these cells within the tumor microenvironment." (PMID 40830700, 2025). "Their proliferating CD4+ counterparts upregulated ENTPD1 (CD39) and ITGAE (CD103), like proliferating CD8+ T cells, and hence this mobilized population is enriched for putative tumor antigen specificity." (PMID 40299576, 2025). "In addition to CD4+ T cells, cytotoxic CD8+ T cells also play an important roles in anti-infection immunity and in clearing tumor cells." (PMID 40229254, 2025). "CD4+ T-cell-derived IFNγ could increase microglial MHCII expression, as observed in our analysis, and then promote microglial phagocytosis of GBM tumor, in a way resembling the report of anti-CTLA-4 treatment." (PMID 39885128, 2025). "They play a pivotal role in priming and activating tumor-specific T cell responses by processing and presenting tumor antigens via MHC class I and II molecules, thereby initiating cytotoxic CD8+ T cell and helper CD4+ T cell responses." (PMID 41244711, 2025). "The transformation of CD4+ TCM cells into CD8+ TRM cells in PAAD tissue appears to be a favorable occurrence, suggesting potential benefits in future PAAD immunotherapy by harnessing the specific anti-tumor effects of these TM." (PMID 40141028, 2025). "On one hand, CD4+ Tregs inhibit the activation, proliferation, and effector functions of various cell types, including NK cells, CD4+ T cells, CD8+ T cells, B lymphocytes, and DCs, thereby contributing to tumor metastasis and progression in different cancer types." (PMID 39860614, 2025). "Additionally, our system showed a durable response with elevated levels of CD4-positive T-cells and the differentiation into durable TSCM/ TCM, opening up the possibility of persistent tumor control and sustained remission in the patients." (PMID 40722088, 2025). "In the tumor microenvironment, MZF1 is mainly found in CD4 Tconv cells and monocytes/macrophages." (PMID 40655141, 2025).
tumor (continued). "To explore the intercellular interactions between tumor and T cells within TME, we applied Ro/e scoring to identify T cell subclusters enriched in the tumor tissues, specifically focusing on CD4_Exhausted, CD8_Teff, CD8_Tc17, Treg_Suppressive, Cycling T cells, CD8_GZMK_ZNF683 and CD8_Exhausted." (PMID 40452847, 2025). "A wealth of anti-tumor lymphocyte subsets was observed infiltrating the ICD-high subtype, including activated B cells, activated CD4+ T cells, activated CD8+ T cells, central memory CD4+ T cells, and effector CD8+ T cells." (PMID 40959101, 2025). "Indeed, the density of CD4+ and CD8+ tumor-infiltrating lymphocytes (TILs) was also remarkably increased in the ARID1A-deficient CRC tumors that received RT and CHK1 inhibitor treatment." (PMID 40750787, 2025). "The therapeutic effect, which prolonged survival, was dependent on NK cells and CD8+ T lymphocytes but not on CD4+ T cells, and did not confer protection against tumor rechallenge." (PMID 41568361, 2025). "Furthermore, IMagRGD promoted the repolarization of TAMs from M2 type to M1 type, increased the percentage of DC maturation and enhanced infiltration of T helper cells (CD4+) and cytotoxic T lymphocytes (CD8+) in the tumor tissues." (PMID 39839492, 2025). "Furthermore, the bacterial epitope recognition enhanced broader tumor immunogenicity, inducing robust production of TNF-α and IFN-γ in CD4+ T cells alongside the expected Th17 response." (PMID 41441899, 2025). "cDC1s cross-present tumor antigens to CD8+ T cells, whereas cDC2s prime CD4+ T cell subsets." (PMID 41035656, 2025). "It suggests that CD4_CXCL13 might interact with CD8+ T cells and B cells in the TME to modulate local tumor immunity in BM." (PMID 40883281, 2025). "Using our IMC data, which preserved the spatial architecture of the TME, we calculated the distances between individual immune cell populations (CD4+ and CD8+ TILs, and CD68+ TAMs), as well as the distances between those immune cell populations and tumor cells." (PMID 40459946, 2025). "Furthermore, bempegaldesleukin (NKTR-214, an immunostimulatory IL-2 prodrug), which is competent in activating and continuously expanding CD4+ T and CD8+ T cells, manifests a synergistic anti-tumor effect when combined with ICIs." (PMID 40191187, 2025). "In the solid compared to the non-solid, TNF expressed in multiple immune cells (Treg, B, DC, CD8 T, CD4 T and macrophages) interacted with TNFRSF21 in epithelial cells which may enhance tumor cell survival and immune evasion 106,107." (PMID 39803458, 2025). "In addition, the proportions of MDSCs and Treg cells (CD4+ CD25+ Foxp3+ T cells) were decreased, suggesting that COF-909-Cu-induced pyroptosis effectively reprogrammed the TME and stimulated anti-tumor immunity." (PMID 40698137, 2025). "The tumor-derived exosomes from the KRAS-mutant NSCLC patients have been found to transform naïve CD4+CD25−T cells to CD4+FoxP3+ Treg-like cells, a process independent of cytokine signaling." (PMID 41184283, 2025). "In the tumor microenvironment, the distribution and function of CD3+, CD4+, and CD8+ T cells also change, and tumor cells might suppress T cell activity through immune checkpoint molecule production and immunosuppressive cytokine secretion." (PMID 40427615, 2025). "Published studies showed that both IL-12 and GM-CSF stimulate potent anti-tumor responses: IL-12 activates IFN-γ production in NK, CD4+, and CD8+ T lymphocytes and induces T-helper 1 (Th1) differentiation, while GM-CSF promotes the maturation and activation of cross-presenting dendritic cells (DCs)." (PMID 40943484, 2025). "CD4+ T cells orchestrate cancer immunity by enhancing antigen presentation, supporting CD8+ T-cell responses, activating innate immune cells, and directly killing tumor cells via granzyme and perforin." (PMID 40634636, 2025).
tumor (continued). "Monitoring chemokine concentrations in peripheral blood and changes in the ratio of CD4+ T and CD8+ T cells could indicate an improvement in the immune status of cancer patients, which may be useful for evaluating the efficacy of tumor treatment in the future." (PMID 40098106, 2025). "Furthermore, we performed multiplex IHC to evaluate the infiltration of CD4+T cells and CD8+T cells along with activation of MAPK pathway in mice tumor sections obtained from vehicle and CBD-treated groups." (PMID 40475776, 2025). "Given the potent CD4+ T cell response elicited by VZV-vax, we sought to determine whether IT administration of the licensed vaccine could confer tumor control." (PMID 40280970, 2025). "We also observed elevated CD4+ and CD8+ T cell infiltration in the tumor tissue of both viral-treated groups, which suggests that the Ad6 backbone, even without cytokine activity, may lead to the induction of an immune response in the tumor." (PMID 40006917, 2025). "Genes downregulated in tumor exhibited a negative correlation with tumor purity and a positive correlation with T cell infiltration, particularly with CD4+ T and CD8+ T cells." (PMID 40567015, 2025). "Conversely, the increased FOXP3+ Tregs and the decreased CD4+ and CD8+ T cells indicate an immunosuppressive microenvironment mediated by SjE16.7, which may facilitate tumor progression." (PMID 41011849, 2025). "In fact, CD4+CD25+ T cell depletion is known to transiently activate CD8+ T cells, and it is plausible that the interaction between these activated CD8+ T cells and ULBP2-expressing tumor cells was enhanced, resulting in chronic NKG2D stimulation." (PMID 40558520, 2025). "The respective receptor, PD-1, is expressed on CD4+ and CD8+ tumor-infiltrating T-cells (TIL)." (PMID 40075663, 2025). "Starting with T cell stimulating receptors, percentages of CD27 expression were highest on blood-circulating CD4+ T cells (87.52 ± 2.57% of CD4+ T cells) and CD8+ T cells (60.59 ± 4.98% of CD8+ T cells) followed by ascites samples and tumor tissues having least CD27+ T cell proportions." (PMID 41221283, 2025). "The results showed that SHROOM4 expression was positively correlated with immune infiltration scores, especially in Tcm_CD8, Tcm_CD4, and Treg cells, indicating that SHROOM4 might attract immune cells to the tumor microenvironment." (PMID 41573567, 2025). "Tumour specimens were stained with multiplex immunofluorescence, and a pathologist selected regions of interest (ROIs), which were scanned at high magnification and analyzed with markers including ATRX, CD8, STING, DAPI, CD4, CD11c and TCRγ/δ." (PMID 39856469, 2025). "Interestingly, although rare, two populations, CD4+ γδ NKT-like cells (Pop 11) and CD8+ γδ NKT-like cells (Pop 13), were almost exclusively tumor-derived, underscoring their selective presence in the TME and near absence in peripheral blood." (PMID 41221282, 2025). "Additionally, these changes significantly decreased the number of tumor-infiltrating CD4+ T cells and increased the CD8+/CD4+ ratio in GC tumors." (PMID 40599798, 2025). "Th1 CD4+ T-cells release pro-inflammatory signals, such as interferon-gamma (IFN-γ) and interleukin-2 (IL-2), which lead to the maturation of APCs and thus enhanced tumor antigen presentation to CD8+ T-cells." (PMID 40362529, 2025). "CD4+ T cells decreased in non-treated tumor-bearing dogs compared to healthy dogs, with a further significant reduction in corticosteroid-treated tumor-bearing dogs." (PMID 40342421, 2025). "Furthermore, the regressing tumor exhibited a rise in both CD163:CD68 and FoxP3:CD4 ratios, suggesting that the inflammation driving STR was associated with an upregulation in immunosuppressive M2 macrophages and regulatory T-cells (Tregs), respectively." (PMID 40594889, 2025).
tumor (continued). "For CD4+ T cells, some studies have reported a role for neoantigen-specific CD4+ T-cell responses in direct tumor clearance, and CD4+ T cells can exert direct antitumor effects independent of CD8+ T cells." (PMID 40426190, 2025). "Furthermore, we find that immune populations excluded from the tumor are denser and enriched with more naive and exhausted CD4+ T cells and antigen-experienced CD8+ T cells than within the tumor boundary." (PMID 40569674, 2025). "CD4+ T cells play dual roles: they help CD8+ T cells become more cytotoxic, and their regulatory T cells (Tregs) release immunosuppressive substances to prevent CD8+ T cells from being active, which accelerates the growth of tumours." (PMID 40579785, 2025). "Thus, in IKE-treated TIPE2−/− LLC-bearing mice, increasing the accumulation of immunostimulatory MDSCs can promote effector CD4+ and CD8+ T cells to infiltrate into the tumor tissues, but restrain the immunosuppressive Tregs." (PMID 39851538, 2025). "In addition, CD4 and CD8 positive cells were characterized in the tumor tissue using immunohistochemical analysis." (PMID 40297576, 2025). "IHC analysis also revealed that in patients with low CEP55 expression, the lymphocyte subpopulation infiltration in the tumor microenvironment was predominantly CD8+ cells, whereas in patients with high CEP55 expression, the infiltration was predominantly CD4+ cells." (PMID 40386043, 2025). "They observed minimal differences in CD8+ T cells across tumor and nonmalignant tissue, while CD4+ T cells showed unique cytotoxic and regulatory states within tumors." (PMID 40361239, 2025). "Interestingly, a combination of high CD4+ and low CD8+ tumor-infiltrating lymphocytes (TILs) predicts poor prognosis in GBM, indicating a complex relationship between T-cell subtypes and outcomes." (PMID 40018519, 2025). "CD4+ T cells, which can differentiate into Tregs (regulatory T cells), also contribute to the immune system’s effectiveness in eliminating cancer cells; however, for this to occur, MHC II must be expressed on tumor cells." (PMID 40430079, 2025). "In addition, the percentages of LAP+ cells in CD4+ T cells, CD8+ T cells, and granulocytes in tumor tissues (TIL) were 52%, 62%, and 37% lower in DHP-treated rats than in untreated rats, respectively." (PMID 40053558, 2025). "Compared to uninfected chickens, the proportion of PD-1+ CD4+ T-cells was significantly higher in the spleen and tumor tissues of chickens with MD than in those without MD." (PMID 40430752, 2025). "In depth analysis enabled us to separate the tumor clusters into GH1 and PRL expressing cells, the immune cells into CD4 T cells, CD8 T cells and monocytes (with subcategories, cf. Immune cell analysis) and structural cells into stem cells, pericytes, fibroblasts and endothelial cells." (PMID 40523964, 2025). "CD4+ T cells, particularly regulatory T cells (Tregs), can suppress CD8+ T-cell proliferation and cytotoxicity through inhibitory cytokines, IL-2 competition, and direct cell–cell contact, contributing to an immunosuppressive tumor microenvironment." (PMID 41008548, 2025). "Additionally, miRNA-200c can lower the number of T-regulatory cells, increase CD4+ and CD8+ T cells within tumors, and enhance the proliferation and effector functions of tumor-specific CD8+ T cells by targeting the PD-1/PD-L1 immune checkpoint pathway." (PMID 39615277, 2025). "The findings indicate the presence of extensive interactions among distinct cell types within the tumor microenvironment of TNBC, including epithelial cells, cancer cells, B cells, myeloid cells, endothelial cells, CD4+ T cells, CD8+ T cells, and plasma blasts." (PMID 41209699, 2025). "In tumors, while blood-TCR-matched CD4+ cells also showed high frequencies of CXCL13+ and Tregs, this is because they were also prevalent among total CD4+ cells, indicating their basal contribution to the immune tumor microenvironment." (PMID 40299576, 2025).